AGAP7P (ArfGAP with GTPase domain, ankyrin repeat and PH domain 7, pseudogene)
Description:
Putative GTPase-activating protein.
Synonyms: bA109G10.1; formerly CTGLF4; AGAP7
Gene: Transcribed unprocessed pseudogene on chromosome 10 (46,109,621 to 46,131,358, forward strand). Ensembl gene ENSG00000264204.
Diseases named in the same sentence as AGAP7P in open-access papers:
AGAP7P is named in the same sentence as 3 diseases in open-access papers, as found by Europe PMC text mining. Sharing a sentence is not in itself a finding about the gene and the disease. The quoted sentences say what the papers report.
prostate carcinoma (1 paper, 2016). A carcinoma that arises from epithelial cells of the prostate gland. "AGAP7P, a non-coding pseudogene, showed 1.38 fold increased expression in tumor tissues in TCGA data, but the role of this non-coding gene in prostate cancer remains unknown." (PMID 26979803, 2016).
AGAP7P also shares sentences with these, for which no sentence is quoted: autism (1 paper); tumor (1).